SNHG6 (small nucleolar RNA host gene 6)
Diseases named in the same sentence as SNHG6 in open-access papers (continued):
Sharing a sentence is not in itself a finding about the gene and the disease.
cervical cancer (6 papers, 2021 to 2025). A primary or metastatic malignant neoplasm involving the cervix. "SNHG6 is highly expressed in cervical cancer tissues and cell lines, especially in SiHa, HeLa and CaSki cells." (PMID 35692795, 2022). "Knockdown of SNHG6 can inhibit tumor cell growth and promote apoptosis, suggesting that SNHG6 plays a role in cervical cancer by promoting tumor cell growth and enhancing radiation resistance." (PMID 35692795, 2022). "Members of the SNHG family regulate radiosensitivity through the ceRNA mechanism; SNHG6 sponges miR-485-3p, releasing STYX protein and thereby enhancing cervical cancer cell resistance to radiotherapy." (PMID 41301542, 2025). "Studies have shown that SNHG6/miR-485-3p/STYX axis contributes to the growth and radiation resistance of cervical cancer cells, thus promoting the progression of cervical cancer." (PMID 35692795, 2022). "For example, in cervical cancer tissues and cells, the lncRNA SNHG6, which is a small nucleolar RNA host gene (SNHG family), was upregulated, knockdown of SNHG6 can improve the radiosensitivity of cervical cancer cells by promoting radiation-induced apoptosis." (PMID 36685972, 2022). "Downregulation of SNHG6 or overexpression of miR-485-3p can reduce the expression level of STYX, while knockdown of miR-485-3p or overexpression of STYX can eliminate the effect of SNHG6 silencing on the growth of cervical cancer cells." (PMID 35692795, 2022).
non-small cell lung carcinoma (6 papers, 2020 to 2024). A group of at least three distinct histological types of lung cancer, including non-small cell squamous cell carcinoma, adenocarcinoma, and large cell carcinoma. "Several studies all found that SNHG6 expression was also significantly increased in non-small cell lung cancer (NSCLC) tissues and cell lines and its high expression was correlated with malignant features of NSCLC." (PMID 32518528, 2020). "SNHG6 regulates the proliferation and migration of non-small cell lung cancer." (PMID 38194709, 2024). "Similarly, miR-485-3p/STYX axis in cervical cancer, and miR-485-3p/VPS45 axis in non-small cell lung cancer are reported to be affected by SNHG6." (PMID 37735423, 2023). "In non-small cell lung cancer, SPI1 exerted an oncogenic role via upregulation of lncRNA SNHG6 and miR-485-3p/VPS45 axis." (PMID 35945192, 2022).
cholangiocarcinoma (5 papers, 2020 to 2023). A carcinoma that arises from the intrahepatic biliary tree (intrahepatic cholangiocarcinoma) or from the junction, or adjacent to the junction, of the right and left hepatic ducts (hilar cholangiocarcinoma). "Overexpression of SNHG6 was associated with enhanced tumor progression and poor survival in subjects with cholangiocarcinoma (CCA)." (PMID 34095461, 2021). "Taken together, these results provided a comprehensive analysis of the role of SNHG6 in CCA cells and offered important clues to understand the key roles of competing endogenous RNA (ceRNA) mechanisms in human cholangiocarcinoma." (PMID 32226515, 2020).
esophageal squamous cell carcinoma (5 papers, 2020 to 2023). Esophageal squamous cell carcinoma (ESCC) is a type of esophageal carcinoma (EC) that can affect any part of the esophagus, but is usually located in the upper or middle third. "SNHG6 expression is upregulated in esophageal squamous cell carcinoma (ESCC) and has an association with TNM stage, metastasis, and poor survival." (PMID 37735423, 2023). "And it has been confirmed in several researches that SNHG6 inhibited apoptosis by regulating EZH2 expression via the sponging of MiR-101-3p in esophageal squamous-cell carcinoma." (PMID 37626362, 2023). "The upregulation of SNHG6 has been reported in esophageal squamous cell carcinoma." (PMID 37735423, 2023). "Also, SNHG6 was reported to encourage proliferation of esophageal squamous cell carcinoma cells and prevent cell apoptosis." (PMID 33009370, 2020).
ovarian carcinoma (5 papers, 2020 to 2025). A malignant neoplasm originating from the surface ovarian epithelium. "By searching related literature and databases, about 30% lncRNAs have been verified to play roles in the regulation of proliferation, invasion, and migration of ovarian cancer cells, including ZFAS1, SNHG1, GAS5, EMX20S, GIHCG, TP53TG1, EPB41L4A-AS1, SNHG8, SNHG6, and HCP5." (PMID 33519912, 2020).
glioblastoma (4 papers, 2020 to 2025). The most malignant astrocytic tumor (WHO grade IV). "The lncRNA small nucleolar RNA host gene 6 (SNHG6) has been implicated in various cancer types, yet its role in glioblastoma remains relatively unexplored." (PMID 39015773, 2024). "Overall, the dysregulation of SNHG6 in glioblastoma suggests its potential as a diagnostic biomarker and therapeutic target for the disease." (PMID 39015773, 2024). "Moreover, high expression levels of SNHG6 in glioblastoma have been associated with advanced tumor stage, poor prognosis, and shorter overall survival of patients." (PMID 39015773, 2024). "However, further research into the precise mechanisms underlying SNHG6’s involvement in glioblastoma pathogenesis is warranted to better assess its therapeutic promise." (PMID 39015773, 2024). "Two studies have reported frequent upregulation of SNHG6 in glioblastoma tissues and cell lines compared to normal brain tissues, suggesting its involvement in glioblastoma development." (PMID 39015773, 2024). "Additionally, the downregulation of SNHG6 in glioblastoma cells induces the expression of the stem cell marker SOX2 and modulates epithelial-mesenchymal transition through interactions with Notch1 and β-catenin." (PMID 39015773, 2024). "Interestingly, both DANCR and SNHG6 are targets of the miR-183/96/182 cluster in the DIANA-LncBase database, which suggests a possible DElncRNA/DEmiRNA interplay in glioblastoma." (PMID 36497269, 2022). "SNHG6 was upregulated in kidney chromophobe (KICH), kidney renal clear cell carcinoma (KIRC), kidney renal papillary cell carcinoma (KIRP), glioblastoma multiforme (GBM) and colon adenocarcinoma (COAD) when compared with non-cancer tissues." (PMID 32655318, 2020).
lymph node metastasis (4 papers, 2020 to 2023). "High expression of SNHG6 was associated with invasion depth, lymph node metastasis, distant metastasis, and TNM stage." (PMID 33842553, 2021). "Our results demonstrated that cancer patients with elevated SNHG6 expression had a higher incidence of lymph node metastasis (OR = 2.59, 95% CI = 1.41–4.77, P = 0.002)." (PMID 32000704, 2020). "Seven studies that included 549 patients presented data about lymph node metastasis (yes vs no) based on the various expression levels of SNHG6." (PMID 32000704, 2020). "The results showed that the expression of SNHG6 was not significantly correlated with the age, gender and racial differences of the patients, while it was significantly upregulated in patients with lymph node metastasis and pathological stage IV (p < 0.01)." (PMID 37004005, 2023).
bladder cancer (3 papers, 2019 to 2023). "The study demonstrated that increased expression of SNHG6 causes EMT in bladder cancer via increasing Snail1/2." (PMID 37735423, 2023). "Wang and colleagues studied the elevated levels of SNHG6 in bladder cancer." (PMID 37735423, 2023). "Thus, SNHG6 accelerates bladder cancer cell progression through miR‐125b/NUAK1 and miR‐125b/Snail1/2 pathways." (PMID 32518528, 2020). "Their data suggested that overexpressed SNHG6 induces EMT through upregulating Snail1/2 and promotes migration and invasion of bladder cancer cells by sponging miR‐125b, thereby activating the target gene of miR-125b-novel (nua) kinase family 1 (NUAK1), also known as ARK5." (PMID 32518528, 2020).
ischaemic stroke (3 papers, 2019 to 2022). "The in vitro functional assays were performed to elucidate the underlying molecular mechanisms of SNHG6 in the pathogenesis of ischaemic stroke." (PMID 31334597, 2019). "To determine the role of SNHG6 in ischaemic stroke, we used OGD‐induced cortical neurons to mimic ischaemic stroke in vitro." (PMID 31334597, 2019). "In conclusion, our study for the first time demonstrated that lncRNA SNHG6 functions as a ceRNA to regulate neuronal death by targeting miR‐181c‐5p/BIM signalling pathway in ischaemic stroke." (PMID 31334597, 2019). "In ischemic stroke LncRNA SNHG6 (small nucleolar RNA host gene 6) promoted neuronal cell apoptosis by inhibiting miR-181c but upregulating its target Bim." (PMID 31812951, 2019). "This study revealed a novel function of SNHG6 in the modulating neuronal apoptosis in the ischaemic stroke model, and the role of SNHG6 in the regulating of neuronal apoptosis was at least partly via targeting miR‐181c‐5p/BIM signalling pathway." (PMID 31334597, 2019). "The lncRNA SNHG6 functions as a ceRNA to regulate neuronal apoptosis in ischaemic stroke." (PMID 36385761, 2022). "TTC staining, quantitative real‐time PCR, cell apoptosis assay, caspase‐3 activity assay, Western blot, RNA immunoprecipitation and luciferase reporter assay were performed to evaluate the function and possible mechanisms of SNHG6 in the pathogenesis of ischaemic stroke." (PMID 31334597, 2019). "This study may provide a better understanding of the functions and potential mechanisms of SNHG6 in the pathogenesis of ischaemic stroke." (PMID 31334597, 2019). "Based on the results from bioinformatics prediction, the downstream targets of SNHG6 were not limited to miR‐181c‐5p, and other predicted miRNAs may be investigated to consolidate the role of SNHG6 in ischaemic stroke." (PMID 31334597, 2019). "This study aimed to examine the functional role of SNHG6 in the ischaemic stroke." (PMID 31334597, 2019). "Further may be warranted to clarify the molecular mechanisms of the cross‐talk signalling pathway regulated by SNHG6 in the pathogenesis of ischaemic stroke." (PMID 31334597, 2019). "As far as we know, the functions and potential mechanisms of small nucleolar RNA host gene 6 (SNHG6) in ischaemic stroke have not been explored." (PMID 31334597, 2019).
Nephroblastoma (3 papers, 2022 to 2023). An embryonal neoplasm characterized by the presence of epithelial, mesenchymal, and blastema components. "Another study showed that SNHG6 was found to be overexpressed in nephroblastoma tissues and knockdown of SNHG6 suppressed cell proliferation, migration and incursion via elevating miR-15a expression." (PMID 35358010, 2022). "miR-15a was reported as a direct target of SNHG6 in Wilms tumor." (PMID 37735423, 2023). "SNHG6 is also an oncogene that is highly expressed in Wilms tumor." (PMID 35592755, 2022).
colon cancer (2 papers, 2020 to 2023). "SNHG6 knockdown suppresses colon tumor growth in a xenograft model." (PMID 37190145, 2023). "Additionally, SNHG6 and SNHG7 are highly expressed in colon cancer, leading to the proliferation of colon and breast cancer cells by sponging miR-181a-5p and miR-186-5p, respectively." (PMID 37190145, 2023).
esophageal cancer (2 papers, 2021 to 2023). A primary or metastatic malignant neoplasm involving the esophagus. "First, we removed lncRNAs with longer than 4000 nucleotides and then eliminated the molecules that have already been studied in esophageal cancer such as H19, SNHG6, LUCAT1, HOXA11." (PMID 34659577, 2021).
non-alcoholic fatty liver disease (2 papers, 2024 to 2026). "Further studies demonstrated that overexpression of SNHG6 accelerates the malignant transformation from non‐alcoholic fatty liver disease (NAFLD) to HCC in a mouse model induced by a high‐cholesterol diet." (PMID 41474641, 2026).
ovarian clear cell cancer (2 papers, 2019 to 2020). An invasive malignant neoplasm that arises from the ovary and is characterized by a predominance of clear and hobnail malignant epithelial cells. "However, little information about the expression pattern of SNHG6 in ovarian clear cell carcinoma (OCCC) is available, and the contributions of this long non‐coding RNA to the tumourigenesis and progression of OCCC are unclear." (PMID 31119871, 2019).
rectal adenocarcinoma (2 papers, 2019 to 2021). "Potential function of SNHG6 in human colon and rectal adenocarcinoma (CRC) was evaluated." (PMID 31533634, 2019).
sarcoma (2 papers, 2021 to 2024). A usually aggressive malignant neoplasm of the soft tissue or bone. "Nevertheless, the function of SNHG6 as a necroptotic gene in sarcoma has not yet been elucidated." (PMID 38194709, 2024).
tongue cancer (2 papers, 2019 to 2020). A malignant neoplasm affecting the tongue. "It was shown that SNHG6 was up-regulated in tongue cancer, and its knockdown inhibited cell viability and proliferation, induced apoptosis and prevented EMT in vitro." (PMID 32947877, 2020). "For instance, expression of the lncRNA SNHG6 is significantly increased in tongue cancer, and interference with SNHG6 expression can inhibit the proliferation and epithelial–mesenchymal transition (EMT) of tongue cancer cells." (PMID 31391008, 2019).
acute myeloid leukemia (1 paper, 2024). Acute myeloid leukemia (AML) is a group of neoplasms arising from precursor cells committed to the myeloid cell-line differentiation. "SNHG6 is a lncRNA with a known impact in several cancer types, and is significantly associated with a poor prognosis in acute myeloid leukemia." (PMID 38419051, 2024).
breast tumors (1 paper, 2022). "Among four splice variants of SNHG6 (202, 203, 204, and 207), SNHG6 203 was proved as an overexpressed splice variant in breast tumors." (PMID 36247503, 2022).
cerebral infarction (1 paper, 2019). An ischemic condition of the brain, producing a persistent focal neurological deficit in the area of distribution of the cerebral arteries. "Knockdown of SNHG6 markedly alleviated cerebral infarction volume when compared to MCAO + siNC group." (PMID 31334597, 2019).
chondrosarcoma (1 paper, 2021). A malignant cartilaginous matrix-producing mesenchymal neoplasm arising from the bone and soft tissue. "To investigate the association between SNHG6 expression and the progression of chondrosarcoma, we first measured the expression of SNHG6 in human chondrosarcoma tissues and normal cartilage tissues by qRT-PCR." (PMID 33431838, 2021). "To ascertain the association among KLF6, EZH2, SP1, and SNHG6 during the progression of chondrosarcoma, we then measured the expression of EZH2 and SP1 in KLF6-overexpressing SW1353 and HCS2/8 cells." (PMID 33431838, 2021). "Here we found that SNHG6 expression was upregulated and showed positive correlation with the progression of chondrosarcoma." (PMID 33431838, 2021). "H&E staining with lung tissues further displayed that there were much more infiltration and invasion of chondrosarcoma cells in the lungs when SNHG6 is normally expressed." (PMID 33431838, 2021). "Functional assays demonstrated that SNHG6 was required for the proliferation, migration, and invasion of chondrosarcoma cells." (PMID 33431838, 2021). "Consistently, all kinds of chondrosarcoma cell lines exhibited upregulated SNHG6 expression, in which HCS2/8 showed the highest expression of SNHG6, followed by SW1353." (PMID 33431838, 2021). "The data showed that SNHG6 expression was elevated in chondrosarcoma tissues when compared with normal cartilage tissues." (PMID 33431838, 2021). "To verify this phenotype, we then assessed the expression of SNHG6 in normal chondrocytes and several available chondrosarcoma cell lines by qRT-PCR, including OUMS-27, SW1353, JJ012, and HCS2/8." (PMID 33431838, 2021). "This novel mechanism is the first report about the function of SNHG6 in chondrosarcoma and revealed that lncRNA SNHG6 and KLF6 played an essential role during the progression of chondrosarcoma." (PMID 33431838, 2021). "Our study showed that SNHG6 expression was upregulated in chondrosarcoma tissues and cell lines, which was induced by SP1 activation." (PMID 33431838, 2021). "In summary, this study reveals that SP1-induced SNHG6 forms a positive loop to facilitate the carcinogenesis of chondrosarcoma through the suppression of KLF6 by recruiting EZH2, which manifests the oncogenic function of SNHG6 in chondrosarcoma." (PMID 33431838, 2021). "In summary, our study revealed that the expression of SNHG6 was upregulated in chondrosarcoma, which was induced by SP1 activation." (PMID 33431838, 2021). "In the present study, we investigated the function and regulatory mechanism of SNHG6 in the carcinogenesis of chondrosarcoma." (PMID 33431838, 2021). "The reciprocal regulation between other transcription factors and lncRNAs, especially SNHG6, in cancer progression suggested that there might be other transcription factors involved in the modulation of SNHG6 in chondrosarcoma." (PMID 33431838, 2021). "In all, these data demonstrated that SNHG6 knockdown could dampen the proliferation, migration, tumorigenesis, and metastasis of chondrosarcoma cells in vitro and in vivo." (PMID 33431838, 2021). "To explore the function of SNHG6 in the progression of chondrosarcoma, we then knocked down SNHG6 by shRNA in both HCS2/8 and SW1353 cells and assessed the influence of SNHG6 knockdown on the proliferation, migration, tumorigenesis, and metastasis of chondrosarcoma cells." (PMID 33431838, 2021). "Moreover, we further analyzed the expression level of SNHG6 in chondrosarcoma tissues in different stages." (PMID 33431838, 2021). "Small nucleolar RNA host gene 6 (SNHG6) is a newly discovered long non-coding RNA (lncRNA), while the regulatory mechanism of SNHG6 in chondrosarcoma is largely unknown." (PMID 33431838, 2021). "However, the function and regulatory mechanism of SNHG6 in chondrosarcoma is still elusive." (PMID 33431838, 2021). "Consistently, the data showed that SNHG6 could interact with EZH2 in chondrosarcoma cells." (PMID 33431838, 2021).
chondrosarcoma (continued). "Mechanistically, augmented SNHG6 recruited EZH2 and inhibited the transcription of tumor-suppressor gene KLF6, which thus promoted the tumorigenesis of chondrosarcoma." (PMID 33431838, 2021). "In the present study, we for the first time found that SP1 induced the upregulation of SNHG6, which then led to the suppression of KLF6 by recruiting EZH2 and promoted the tumorigenesis of chondrosarcoma." (PMID 33431838, 2021). "SNHG6 suppressed the transcription of tumor-suppressor gene KLF6 through EZH2, which further promoted the tumorigenesis of chondrosarcoma." (PMID 33431838, 2021). "Nevertheless, whether SNHG6 exerted similar function in the development of chondrosarcoma is not clear." (PMID 33431838, 2021). "Moreover, we checked the influence of SNHG6 knockdown on the migration and invasion of SW1353 and HCS2/8 cells by transwell assay; consistently, both experiments showed that SNHG6 knockdown restrained the migration and invasion of chondrosarcoma cells." (PMID 33431838, 2021).
clear cell renal cell carcinoma (1 paper, 2021). "Overexpression of SNHG6 was found to promote cell proliferation and metastasis in clear cell renal cell carcinoma (ccRCC) by interacting with YBX1." (PMID 34290738, 2021).
colorectal tumor (1 paper, 2022). "SNHG6 could be applied as a consideration to differentiate tumor and non-tumor tissues and grade definition in colorectal malignancies, and it could participate in colorectal tumor formation as a cell cycle progressive factor." (PMID 35096086, 2022). "Consistent with previous studies, we observed that lncRNA SNHG6 was upregulated in colorectal tumor tissues compared to non-tumor marginal tissues." (PMID 35096086, 2022). "Previous studies have shown that the expression level of SNHG6 RNA is higher in colorectal tumor tissues than in non-tumor tissues, indicating lncRNA SNHG6 as a valuable prognostic biomarker." (PMID 35096086, 2022).